SMIM17 (small integral membrane protein 17)
Tractability: Antibody: UniProt predicts a signal peptide or a membrane-spanning region.
Gene: Protein-coding gene on chromosome 19 (56,643,159 to 56,657,247, forward strand). Ensembl gene ENSG00000268182.
Subcellular location: Membrane
Subcellular location (Human Protein Atlas): Vesicles
Gene Ontology:
Cellular component: membrane
Genetic constraint (gnomAD): Loss-of-function variants: 5 observed, 10.05 expected, observed/expected ratio (o/e) 0.5, 90% interval 0.26 to 1.05. The upper end of that interval is the gene's LOEUF score, 1.05, which puts it in group 4 of 6, group 1 being the genes least tolerant of losing a copy. Missense variants: 106 observed, 103.51 expected, observed/expected ratio (o/e) 1.02, 90% interval 0.87 to 1.2. Synonymous variants: 37 observed, 39.49 expected, observed/expected ratio (o/e) 0.94, 90% interval 0.72 to 1.23.
Homologues: Orthologues: chimpanzee SMIM17 (100% identical), macaque SMIM17 (98% identical), mouse Smim17 (83% identical), pig SMIM17 (82% identical), rat Smim17 (81% identical), guinea pig SMIM17 (79% identical), rabbit SMIM17 (78% identical), dog SMIM17 (75% identical).